RNU6-246P (RNA, U6 small nuclear 246, pseudogene)
Gene: Small nuclear RNA gene on chromosome 9 (15,544,188 to 15,544,294, forward strand). Ensembl gene ENSG00000207433.
Homologues: Orthologues: chimpanzee U6 (99% identical), pig U6 (86% identical), dog U6 (82% identical), mouse Gm24502 (79% identical), rat LOC120096756 (79% identical). Paralogues in human: RNU6-140P (94% identical), RNU6-1124P (90% identical), RNU6-16P (89% identical), RNU6-17P (89% identical), RNU6-18P (89% identical), RNU6-25P (89% identical), RNU6-29P (89% identical), RNU6-338P (89% identical), RNU6-33P (89% identical), RNU6-480P (89% identical), RNU6-664P (89% identical), RNU6-756P (89% identical), and 1283 more.